PPARA (peroxisome proliferator activated receptor alpha)
Diseases named in the same sentence as PPARA in open-access papers (continued):
Sharing a sentence is not in itself a finding about the gene and the disease.
cholestasis (continued). "Given the pivotal role of PPARα in liver lipid homeostasis and the treatment of fenofibrate, severe as a PPARα agonist, against cholestasis-induced hepatic injury, the expression of APOA2 and PPARα was detected by western blotting to verify the relationship between ICP and control groups." (PMID 38177949, 2024). "The findings also strongly suggest that FFA-induced PPARα activation (agonism) may be a fundamental mechanism contributing to the liver-protective effects of cis-TSG against ANIT-induced cholestasis." (PMID 39635428, 2024). "PPARα activators are promising in the treatment of cholestasis." (PMID 35924060, 2022). "However, PPARα is involved in the control of bile acid homeostasis, and the treatment of inflammation during cholestasis provides us new perspective to treat this disease." (PMID 35924060, 2022). "In addition, natural PPARα activators are necessary for the treatment of cholestasis as they can suppress hepatocyte apoptosis, necrosis, and fibrosis." (PMID 35924060, 2022). "However, the regulation of PPARα in cholestasis, including the crosstalk of PPARα and FXR, is still unclear." (PMID 35924060, 2022). "The expression of genes related to bile acid metabolism is included in the factors regulated by PPARα, and PPARα agonists may improve cholestasis." (PMID 33947390, 2021). "Interestingly, the three fibrates showed different trends in prevention of EE-CPZ cholestasis in the presence of this PPARα blocker." (PMID 23997763, 2013). "Our study shows that PPARα activation decreases apoptosis in an experimental model of cholestasis." (PMID 18045488, 2007). "Importantly, PPARα agonists, e.g., fenofibrate, have shown therapeutic benefits in reducing elevated markers of cholestasis in patients with PBC and PSC, and elafibranor, the first PPAR (dual α, β/δ) agonist, has been FDA-approved for the second-line treatment of PBC." (PMID 39120326, 2024). "Therefore, finding safe and effective PPARα activators may have important clinical significance for the amelioration of cholestasis." (PMID 35924060, 2022). "These evidences suggested that PPARα could attenuate cholestasis induced by ANIT." (PMID 28855630, 2017). "Finally, the anti-inflammatory effects of PPARα could also add to potential beneficial effects in cholestasis." (PMID 23540496, 2013). "The potent induction of FGF21 by PPARA and the effect of its agonist on cholestasis are already known, and the linkage between PPARD and PPARA in the regulation of cholestasis is a subject for future research." (PMID 39899669, 2025). "For PPARα and NR1H4 expression we used liver biopsy dataset GSE65359 (84 cases of hepatitis B), fetal and adult liver sample dataset GSE61276 (106 cases), and cholestasis gene expression excluding BA." (PMID 36090996, 2022). "It has been found that BAK can increase serum ALT, TBIL, and TBA and reduce CYP7a1, HMG-CoA, PPARα, and SREBP-2 mRNA expression, resulting in cholestasis hepatotoxicity." (PMID 36193146, 2022). "For instance, inhibitors targeting NRF2-coactivator interactions or agonists restoring PPARα and FXR activity might counteract cholestasis or other metabolic dysfunctions in diseases including PFIC5 or NAFLD." (PMID 40565288, 2025). "Thus, the crosstalk between basal PPARα and FXR occurred, and adaptation of bile acid metabolism was inhibited in chronic cholestasis." (PMID 35924060, 2022). "In addition to HNF1α and FXR, there are many others nuclear receptors that also participate in bile acids metabolism, such as CAR, PPARα, and SRT1720 may also affect them to alleviate ANIT-induced cholestasis; thus, additional experiments are needed to determine its mechanism." (PMID 28553227, 2017). "Moreover, ligands of PPARα may play a role in the regulation of bile excretory function trough up-regulation human MDR3 expression, which is localized to the canalicular membrane of hepatocytes, where it is the major determinant of biliary salts secretion, thereby reducing cholestasis." (PMID 37371808, 2023).
pancreatic cancer (32 papers, 2008 to 2026). "On the other hand, PPARα is overexpressed in pancreatic cancer tissues when compared with their adjacent normal tissues." (PMID 33959154, 2021). "PPARα agonists were recently reported to induce proliferation arrest by negatively regulating cell cycle in pancreatic cancer and reduce primary and metastatic non-small cell lung cancer growth." (PMID 27323819, 2016). "Notably, PPARα-based therapies such as clofibrate and fenofibrate have already been investigated for their anti-cancer effects in pancreatic cancer, with promising pre-clinical evidence in both cell lines and animal models." (PMID 39941724, 2025). "PPARα was found to induce carnitine palmitoyltransferase 1C (CPT1C) in a breast and a pancreatic cancer cell line, leading to the activation of cell proliferation." (PMID 35954274, 2022). "Moreover, there were several cancer-related pathways such as pancreatic cancer and small cell lung cancer identified in mice without WY14643 treatment especially in liver, which indicated that PPARα was thought to play an important role in prevention of cancer development." (PMID 21811494, 2011).
Hypoglycemia (31 papers, 2007 to 2026). A decreased concentration of glucose in the blood. "Loss or knockdown of PPARα leads to fasting-induced hypoglycemia and reduced hepatic glucose levels, highlighting its essential role in maintaining glucose homeostasis." (PMID 41438090, 2025). "When mitochondrial β-oxidation was pharmacologically blocked in mice deficient in PPARα (PPARα-/-), TG accumulated in liver and the animals died from hypoglycemia." (PMID 20863371, 2010). "Interestingly, PPARα-deficient mice have been reported to demonstrate impaired FA oxidation, lipid accumulation in liver, and hypoglycemia under fasting conditions." (PMID 40806595, 2025). "Thus, the major cause of the sesame-induced death in PPARα-null mice during a short period would be severe hypoglycemia." (PMID 22577367, 2012). "However, studies of PPARα-null mice subjectedto fasting indicated that PPARα deficiency can causesevere hypoglycemia." (PMID 17389764, 2007). "Although not all studies are in agreement, a dual block in the early steps of the conversion of lactate to glucose and glycerol to glucose in PPARα−/− mice causes a maladaptation to fasting and may at least partly explain the development of hypoglycemia in these mice." (PMID 20936117, 2010). "AOP 1 in this putative AOP network consists of PPARα activation as one of multiple initiating events, with placental insufficiency, neonatal hepatic glycogen deficit, and hypoglycemia as key events leading to neonatal mortality and lower birth weight." (PMID 41920860, 2026). "PPARα controls not only lipid metabolism but also influences glucose metabolism, and fasted global Ppara−/− mice are widely reported to develop severe hypoglycemia." (PMID 41460648, 2026). "Given the ability of PPARα to regulate flavoprotein gene expression, we pursued additional RNA-Seq studies to understand the mechanisms that allowed fenofibrate to rescue hypoglycemia in B2D." (PMID 37417957, 2023). "CD8+ TILs experiencing both hypoxia and hypoglycemia within the TME enhance PPARα signaling and fatty acid catabolism to preserve their energy production and effector functions." (PMID 39872079, 2022). "PPARα-null mice develop a phenotype characterized by hypoglycemia, hyperlipidemia, hypoketonemia and fatty liver due to their inability to meet energy demands in a fasting state." (PMID 30893897, 2019). "In these cases, both hypoglycemia/steatohepatitis and cholesterol phenotypes were reversed by the administration of a PPARα agonist such as WY14643." (PMID 30893897, 2019). "In particular, PPARα knock-out mice show severe hypoglycemia and depleted hepatic glycogen stores during fasting." (PMID 28282965, 2017). "Indicative of the integral role for PPARα in the gluconeogenic response to fasting, PPARα null mice display fasting hypoglycemia." (PMID 27708682, 2016). "In any case, acute hypoglycemia alone cannot explain chronic effect of feeding sesame seeds on PPARα-null mice." (PMID 22577367, 2012). "After the reduction, wild-type mice recovered the serum glucose levels to normal, but the severe hypoglycemia persisted for several days in most PPARα-null mice." (PMID 22577367, 2012). "Fasted PPARα−/− mice suffer from severe hypoglycemia starting already several hours after food withdrawal." (PMID 20936117, 2010). "It has been reported repeatedly that although the general appearance of PPARα−/− mice is normal in the fed state, they develop severe hypoglycemia during fasting." (PMID 20936117, 2010). "Gluconeogenesis is fuelled by energy generated through β-oxidation, and fasted PPARα-/- mice develop fatty liver and hypoglycemia." (PMID 20863371, 2010). "Pparα−/− mice exhibit lower quantities of hepatic glycogen, which might contribute to rapid hypoglycemia during the early hours of fasting." (PMID 40565288, 2025).
Hypoglycemia (continued). "PPARα regulates the transcription of key gluconeogenic enzymes, including phosphoenolpyruvate carboxykinase (PEPCK) and glucose-6-phosphatase (G6Pase), and its deficiency impairs hepatic glucose output, resulting in persistent hypoglycemia." (PMID 41438090, 2025). "PPARα−/− mice exhibited fasting hypoglycemia as previously reported." (PMID 38604598, 2024). "The liver-specific FASN knock-out (FASKOL) mice even developed hypoglycemia and fatty liver on a zero-fat diet, which was reasoned as the interference of PPARα activation, disruption of the transcription of genes critical for fatty acid oxidation, as well as interfered gluconeogenesis." (PMID 35052685, 2021). "Overall, based on the effects of PPARα on glucose homeostasis and its important regulatory role in the transition from feeding to fasting, PPARα might be involved in protecting against hypoglycemia during CR." (PMID 32708786, 2020). "Several different mechanisms were put forward to explain the fasting-induced hypoglycemia in PPARα−/− mice, some of which may be operative simultaneously." (PMID 20936117, 2010). "For a start, fasting PPARα−/− mice display marked hypoglycemia (see Section 3.1)." (PMID 20936117, 2010). "Inasmuch as the conversion of glycerol to glucose in liver is impaired in PPARα−/− mice, defective synthesis of glucose from glycerol may partly explain the fasting-induced hypoglycemia in PPARα−/− mice." (PMID 20936117, 2010). "However, the suggested involvement ofPPARα in glucose homeostasis could imply that the increaseof PPARα in mice subjected to CR is a mechanism protectingthese animals from hypoglycemia." (PMID 17389764, 2007). "Furthermore, fasted global Ppara−/− mice reportedly exhibit more severe hypoglycemia than fasted liver‐specific Ppara‐null (Ppara∆HEP) mice, suggesting the contribution of extra‐hepatic PPARα to systemic glucose metabolism." (PMID 41460648, 2026). "On the other hand, KD-fed PPARα−/− mice (PPARα−/−/KD) died after marked hypoglycemia for a few days after KD feeding (data not shown)." (PMID 38604598, 2024). "The direct inhibition of FASN might trigger chronic on-target safety risks due to the reduced β-oxidation of fatty acids by compromising the activity of PPARα, since FASKOL mice showed lipid accumulation and hypoglycemia with a zero-fat diet or fasting." (PMID 35052685, 2021). "Importantly, 1,3-BD administration ameliorated fasting hypoglycemia in PPARα−/− mice by increasing the blood BHB concentration without transactivation of hepatic Hmgcs2 expression." (PMID 38604598, 2024). "However, for mice fed a high PUFAs diet (FISH), hypoglycaemia was not significantly different in fasted Pparα−/− mice compared to wild-type mice, though there was a trend towards reduced glycaemia." (PMID 27669233, 2016).
Stroke (31 papers, 2008 to 2025). Sudden impairment of blood flow to a part of the brain due to occlusion or rupture of an artery to the brain. "Further bioinformatic analysis of our RNA-seq data revealed the upregulation of other genes in the IL6/JAK/STAT3 expression signatures in mouse stroke brains upon the loss of PPARα, as well." (PMID 40362325, 2025). "We also identified many other differentially expressed genes (DEGs) upon the loss of PPARα that correlated with increased infarct size in our stroke model." (PMID 40362325, 2025). "PPARα KO brains had upregulated expression of several genes already implicated in neural injury following stroke such as Mmp19, Il6, Saa3, and Il1r2." (PMID 40362325, 2025). "Although we observed PPARα KO-associated modulation of several pathways linked to increased infarct volume in male stroke brains, it is possible that PPARα modulates transcriptional pathways in the CNS differently between males and females." (PMID 40362325, 2025). "Through bioinformatic analysis on our RNA-sequencing data, we were able to identify several PPARα KO-regulated transcriptional pathways associated with increased stroke infarct sizes." (PMID 40362325, 2025). "Oral administration of PPARα agonists decreased the incidence of stroke in apolipoprotein-E deficient mice and reduced the cerebral infarct volume in wild-type mice following transient middle cerebral artery occlusion (MCAO)." (PMID 19789638, 2010). "Therefore, PPARα likely restrains the expression of genes linked to IL6/JAK/STAT3 signaling to prevent rampant neuroinflammation in the subacute stroke phase." (PMID 40362325, 2025). "The authors subjected wild-type and apolipoprotein E-deficient (ApoE−/−) mice to middle cerebral artery occlusion and identified that the PPARα agonist fenofibrate decreased the susceptibility of ApoE−/− mice to stroke and also decreased infarct volume in wild-type animals." (PMID 25705219, 2015). "We used a well-established model of cerebral ischemia in PPARα transgenic mice and conducted the RNA sequencing (RNA-seq) of mouse stroke brains harvested 48 h post-middle cerebral artery occlusion (MCAO)." (PMID 40362325, 2025). "This highlights a potential neuroprotective role of PPARα-mediated gene repression in the brain following stroke." (PMID 40362325, 2025). "Compared with brains from MCAO/R WT mice, brains from MCAO/R PPARα KO mice had significantly larger infarct sizes, indicating greater stroke severity (Figure A1)." (PMID 40362325, 2025). "Although previous studies in animal models of stroke have reported neuroprotective effects from treatment with PPARα agonists like fenofibrate, further genetic approaches are needed to corroborate these findings." (PMID 40362325, 2025). "PPARα knockout (KO) increased brain infarct size following stroke, indicating a protective role of PPARα in brain ischemia." (PMID 40362325, 2025). "Nevertheless, our study highlights PPARα as an attractive candidate for pharmacological stroke therapy that warrants further research." (PMID 40362325, 2025). "PPARα functions as a ligand-activated transcription factor, and we identified hundreds of genes that were differentially regulated in the post-stroke brain upon its genetic deletion." (PMID 40362325, 2025). "Together, these studies highlight PPARα agonists as potential pharmacological candidates for stroke therapy." (PMID 40362325, 2025). "We conducted Ingenuity Pathway Analysis (IPA) on our RNA-seq data to further interrogate the cellular pathways affected by PPARα KO in mouse stroke brains." (PMID 40362325, 2025). "We further analyzed our RNA-seq data to identify enriched or depleted cellular pathways resulting from PPARα KO in mouse stroke brains." (PMID 40362325, 2025). "Overall, we found 166 downregulated and 140 upregulated genes in PPARα KO stroke brains with a fold change >1.5 in either direction (FDR < 0.05)." (PMID 40362325, 2025).
Stroke (continued). "We first compared the overall transcriptomes of PPARα KO mouse stroke brains with those of WT stroke brains (PPARα KO MCAO vs. WT MCAO)." (PMID 40362325, 2025). "We performed RNA-seq on ipsilesional hemisphere brain tissue harvested from mice at 48 h post-MCAO to investigate the effects of PPARα KO on gene expression during the subacute stroke phase." (PMID 40362325, 2025). "We also observed the upregulation of a pro-inflammatory tumor necrosis factor alpha (TNFα) gene signature in the brains of PPARα KO mice following stroke." (PMID 40362325, 2025). "We also noted a higher expression of Socs3 (suppressor of cytokine signaling 3) in PPARα KO brains after stroke." (PMID 40362325, 2025). "Similar to GSEA, IPA revealed significant transcriptional reprogramming of TNFα signaling gene signatures in PPARα KO stroke brains 48 h post-MCAO." (PMID 40362325, 2025). "The overall expression pattern of the downstream targets indicates that TNFα is an activated upstream regulator in PPARα KO stroke brains compared with WT stroke brains (Figure A3)." (PMID 40362325, 2025). "To further characterize cellular processes affected in stroke brains by the genetic deletion of PPARα, we conducted gene set enrichment analysis (GSEA) on DEGs between PPARα KO MCAO and WT MCAO brain transcriptomes." (PMID 40362325, 2025). "In agreement, we also observed an increased expression profile for many genes known to be upregulated by TNFα in stroke brains from PPARα KO mice." (PMID 40362325, 2025). "In the present study, we found a high prevalence of carotid atherosclerosis in the high-risk stroke population in China and also identified the associations of variants in IL1A rs1609682, PPARA rs4253655, and HABP2 rs7923349 with carotid atherosclerosis." (PMID 37292135, 2023). "Several studies have demonstrated that PPARA-mediated reduction in oxidative stress correlates with improved outcomes in rodent stroke models." (PMID 35035503, 2022). "To summarize, our report indicates that a brief 1-week course of PPARα/γ agonist aleglitazar initiated post-event affords stroke protection/recovery in a model of mild brain ischemia." (PMID 31147725, 2019). "In aggregate, a brief course of PPARα/γ agonist aleglitazar initiated post-event affords stroke protection and functional recovery in a model of mild brain ischemia." (PMID 31147725, 2019). "The impact of fenofibrate, a peroxisome proliferator-activated receptor-alpha (PPAR-α) agonist, on the risk of thrombolysis-induced hemorrhage during the acute phase of stroke in a rat model of stroke was studied." (PMID 26106408, 2015). "In vivo treatment with PPARα agonist,fenofibrate and WY-14643, reduced the infarct sizein mousemodels of stroke." (PMID 18670616, 2008). "Thus, our data also suggest a link between PPARα and the expression of antioxidant genes post-stroke." (PMID 40362325, 2025). "Thus, PPARα likely curtails neuroinflammation following stroke through the regulation of TNFα signaling-related genes." (PMID 40362325, 2025). "Gene set enrichment analysis (GSEA) and Gene Ontology (GO) analysis revealed the upregulation of gene signatures for the positive regulation of leukocyte proliferation, apoptotic processes, acute-phase response, and cellular component disassembly in mouse stroke brains with PPARα KO." (PMID 40362325, 2025). "Specifically, PPARα KO led to increased expression levels of Gadd45b, Nppa, Hdc, Lcn2, Il6, Sox4, Marcksl1, Saa3, Ucn2, Met, Dusp10, Elovl7, Ngf, C3, Il11, Hmox1, Alox5, Tnfsf9, Angptl4, Plin2, H19, Csf2rb, Atf3, and Col7a1 following stroke." (PMID 40362325, 2025). "In addition, pathway analysis of our RNA-seq data revealed that TNFα signaling, IL6/STAT3 signaling, and epithelial–mesenchymal transition (EMT) gene signatures were increased in PPARα KO stroke brains." (PMID 40362325, 2025).